EGFR (epidermal growth factor receptor)
Diseases named in the same sentence as EGFR in open-access papers (continued):
Sharing a sentence is not in itself a finding about the gene and the disease.
esophageal squamous cell carcinoma (continued). "Therefore, we analyzed the protein expression and gene copy variation of the epithelial growth factor receptor (EGFR) in Chinese esophageal squamous cell carcinoma (ESCC) and explored the possible associations with various features of the tumors and survival of the patients." (PMID 25953424, 2015). "EGFR expression is frequently detected in esophageal squamous cell carcinoma and adenocarcinoma." (PMID 24945674, 2014). "Epidermal growth factor receptor (EGFR) is reportedly overexpressed in most esophageal squamous cell carcinoma (ESCC) patients, but anti-EGFR treatments offer limited survival benefits." (PMID 38937446, 2024). "Pathological analyses have shown that high EGFR expression occurs in 70–88% of patients with esophageal squamous cell carcinoma (ESCC) which correlates with poor prognosis." (PMID 28038457, 2017). "CMTM7 restoration in esophageal squamous cell carcinoma (ESCC) cell lines inhibits cell growth, promotes epidermal growth factor receptor (EGFR) internalization, and suppresses the AKT signaling pathway." (PMID 26528697, 2015). "EGFR is expressed in 33.3% of esophageal squamous cell carcinomas (ESCCs), Lapatinib can have a significant therapeutic effect against EGFR-expressing ESCC by inhibiting the growth of ESCC cells and augmenting Herceptin- and Cetuximab-mediated ADCC." (PMID 24551190, 2014). "In particular, we and others have reported that the overexpression of EGFR is present in 50–70% of oesophageal squamous cell carcinoma (ESCC) cases, and is indicative of a poor prognosis." (PMID 20029417, 2010). "Our study aimed to observe the correlation between epidermal growth factor receptor (EGFR) and programmed cell death-ligand 1 (PD-L1) expression and evaluate prognostic potential of their co-expression in esophageal squamous cell carcinoma (ESCC) patients." (PMID 36812484, 2023). "RNF128 regulates the expression of MMP-2 by activating the EGFR/MAPK signaling pathway, thereby promoting the invasion and metastasis of esophageal squamous cell carcinoma." (PMID 38143380, 2023). "From the clinical point of view, EGFR gene amplifications have been related to adverse clinical outcomes in SCC from different sites, including esophagus SCC, uterine cervix SCC, and oral SCC, among others." (PMID 35565304, 2022). "This study evaluated the antitumor efficacy of the EGFR/HER2 inhibitors, gefitinib and lapatinib, in combination with the IGF-1R inhibitor, linsitinib, on the esophageal squamous cell carcinoma (ESCC)." (PMID 36142299, 2022). "Kyse30 squamous cell esophageal carcinoma cells and FaDu squamous cell pharyngeal carcinoma were chosen to delineate effects of EpEX and EGF on EGFR signaling based on their responsiveness to EGFR-mediated EMT." (PMID 36076232, 2022). "In esophageal squamous cell carcinoma, the overexpression of RNF128 promotes signaling through the EGFR/MAPK/MMP-2 pathway to enhance cell invasion and metastasis." (PMID 33962392, 2021). "Oesophageal squamous cell carcinoma (ESCC) patients whose tumours have EGFR CNG and/or EGFR protein overexpression may represent a subgroup that benefits from EGFR inhibitor monotherapy." (PMID 33169187, 2021). "In esophageal squamous cell carcinoma (ESCC), 64Cu-cetuximab was shown to be useful in detecting EGFR-expressing tumors using PET imaging; however, 64Cu-cetuximab tumor accumulation only peaked at 48 hours (h), indicating that a desired image was produced 2 days later." (PMID 34575943, 2021). "DESC1 was demonstrated to be a tumor suppressor that cleaves EGFR and inhibits AKT activation that sensitizes cell death in esophageal squamous cells carcinoma." (PMID 34064422, 2021). "In esophageal squamous cell carcinoma, PTP1B promotes cell invasion and migration by dephosphorylating MYH9 at Y1408, which results in increased EGFR expression." (PMID 34606417, 2021). "However, EGFR‐targeted ADC therapy for esophageal squamous cell carcinoma (ESCC) is exceedingly rare." (PMID 30372581, 2019).
esophageal squamous cell carcinoma (continued). "Epidermal growth factor receptor (EGFR) is a rational target for cancer therapy, because its overexpression plays an important oncogenic role in a variety of solid tumors; however, EGFR‐targeted antibody–drug conjugate (ADC) therapy for esophageal squamous cell carcinoma (ESCC) is exceedingly rare." (PMID 30372581, 2019). "In agreement with our data, a link between EGFR and IGFBP-3 has also been described for primary human esophageal cells and esophageal squamous cell carcinomas indicating that EGFR indeed directly regulates IGFBP-3." (PMID 29445126, 2018). "Through the follow-up data of esophageal squamous cell carcinoma patients, a univariate logrank survey showed that ADAM17 and EGFR were prognostic factors affecting esophageal squamous cell carcinoma (All P<0.05)." (PMID 25351873, 2015). "In esophageal squamous cell carcinoma (ESCC), about 30.8% of the tumor cells presented EGFR overexpression in relation to the bad prognosis and long-term survival." (PMID 22252115, 2012). "Furthermore, in esophageal squamous cell carcinoma, CALM1 was shown to promote tumor progression and reduce sensitivity to EGFR inhibitors." (PMID 40823088, 2025). "Current evidence for the combined use of immunotherapy, low-dose chemoradiotherapy, and epidermal growth factor receptor-targeted therapy for the treatment of advanced esophageal squamous cell carcinoma is lacking." (PMID 40224180, 2025). "EGFR was not or weakly expressed in chronic esophageal mucosal inflammation tissues with a positive expression rate of 23.33%, but 67.50% in esophageal squamous cell carcinoma tissues." (PMID 36467103, 2022). "Epidermal growth factor receptor (EGFR), a tyrosine kinases receptor (RTK) of ErbB family, is over-expressed in some cancers, including esophageal squamous cell carcinoma (ESCC)." (PMID 34393797, 2021). "It is tempting to speculate that PROS1-driven AXL expression may lead to functional receptor heterodimerization with EGFR, as was shown for HNSCC and esophageal squamous cell carcinoma." (PMID 28118606, 2017). "The follow-up data showed that the esophageal squamous cell carcinoma ADAM17 expression was an important prognostic factor affecting the esophageal squamous cell carcinoma, it had independent prognostic significance as EGFR, lymph node metastasis and TNM stage." (PMID 25351873, 2015). "In esophageal squamous cell carcinoma, circRNA ciRS-7 affects the epidermal growth factor receptor AKT-mTOR signaling pathway, thus inhibiting the autophagy of ESCC cells." (PMID 38338839, 2024). "Epidermal growth factor receptor (EGFR) is suggested to predict the radiosensitivity and/or prognosis of human esophageal squamous cell carcinoma (ESCC)." (PMID 23232108, 2012). "Besides, CMTM7 can inhibit the growth of esophageal squamous cell carcinoma (ESCC) and non-small cell lung cancer (NSCLC) by suppressing EGFR/AKT signaling." (PMID 36829181, 2023). "The cytotoxicity of bispecific energized fusion protein Ec-LDP-Hr-AE was carried out on four human esophageal squamous cell carcinoma (ESCC) cell lines expressing different levels of EGFR and HER2 and the EGFR/HER2 negative NIH 3T3 cells by using MTT assays." (PMID 24664246, 2014). "The current study demonstrated that Ec-LDP-Hr had high affinity to bind to esophageal squamous cell carcinoma (ESCC) cells, and enediyne-energized fusion protein Ec-LDP-Hr-AE showed potent cytotoxicity to ESCC cells with differential expression of EGFR and HER2." (PMID 24664246, 2014). "Additionally, PTK7 promotes proliferation, migration, and invasiveness of esophageal squamous cell carcinoma (ESCC) cells by activating fibroblast growth factor receptor 1 (FGFR1) and contributes to epidermal growth factor receptor (EGFR)/Akt signaling in TNBC cells." (PMID 39936972, 2025).
esophageal squamous cell carcinoma (continued). "Of the 80 cases of esophageal squamous cell carcinoma, 53 cases showed positive ADAM17 expression, 40 of which had positive EGFR expression, while of the 27 cases that were negative for ADAM17 expression, 9 cases had positive EGFR expression." (PMID 25351873, 2015).
osteosarcoma (123 papers, 2007 to 2026). A usually aggressive malignant bone-forming mesenchymal neoplasm, predominantly affecting adolescents and young adults. "According to the expected core targets of the PPI network that were significantly associated with anti-osteosarcoma effects, the top five target proteins (EGFR, Caspase-3, ESR1, HSP90AA1, and SRC) ranked by degree value were subjected to molecular docking." (PMID 40991530, 2025). "It is reported that all osteosarcoma tissues and cell lines commonly express EGFR membrane receptors and are associated with osteosarcoma cell differentiation, proliferation and migration." (PMID 36234645, 2022). "Overactivity of EGFR is frequently observed in osteosarcoma and becomes an underlying therapeutic target." (PMID 35071320, 2021). "With focus on the concomitant activation of EGFR and STAT3 as determinants of osteosarcoma progression, we investigated the mechanisms underlying the anticancer effects of SC, a cantharidin analogue, alone and in combination with the EGFR inhibitor erlotinib." (PMID 31422383, 2019). "The biodistribution of 125I-labeled OI-3 antibody variants was compared with 125I-labeled chimeric anti-EGFR antibody cetuximab in nude mice with subcutaneous OHS osteosarcoma xenografts." (PMID 27776176, 2016). "Amplification and mutation of the epidermal growth factor receptor (EGFR) gene represent signature genetic abnormalities encountered in osteosarcoma." (PMID 27830833, 2016). "In contrast, high EGFR expression was associated with significantly shorter survival times and disease free intervals in canine osteosarcomas." (PMID 26526352, 2015). "GAK appears to be essential for cell death because co-administration of gefitinib and luteolin to EGFR-deficient U2OS osteosarcoma cells also had a greater effect on cell viability than administration of either compound alone." (PMID 24971999, 2014). "Moreover, EGFR expression in osteosarcoma cells is associated with poor prognosis and local recurrence and metastasis." (PMID 36234645, 2022). "Collectively, our results demonstrated that DUSP3 regulates the stemness of osteosarcoma cells through the EGFR/STAT3/SOX2 axis." (PMID 39744427, 2025). "DUSP3 impairs osteosarcoma cells proliferation, migration, invasion, and stemness through regulating the EGFR/STAT3/SOX2 axis." (PMID 39744427, 2025). "In conjunction with our earlier in vitro research, we can infer that DUSP3 inhibits osteosarcoma development and lung metastasis in vivo through regulating EGFR/STAT3/SOX2 axis." (PMID 39744427, 2025). "MYLK4 accelerates tumour progression through activation of epidermal growth factor receptor signalling in osteosarcoma." (PMID 40463716, 2025). "We found that DUSP3 affected osteosarcoma proliferation, migration, and invasion by regulating the Epidermal Growth Factor Receptor (EGFR)/STAT3/SOX2 axis." (PMID 39744427, 2025). "Evidence suggests that low expression of the E3 ubiquitin ligase c-CBL protein is closely associated with high expression levels of epidermal growth factor receptor (EGFR) and platelet-derived growth factor receptor alpha (PDGFRα) in osteosarcoma tissues." (PMID 39062505, 2024). "The epidermal growth factor receptor (EGFR) is overexpressed in osteosarcoma and is a common genetic abnormality related to osteosarcoma." (PMID 38338373, 2024). "More recently, it has been reported that DATS significantly inhibits proliferation, migration, and EMT, promotes cell apoptosis, and induces autophagy in osteosarcoma cells trough the inactivation of the EGFR/PI3K/AKT/mTOR pathway." (PMID 38786044, 2024). "This study aims to determine the correlation between immunoexpression of STAT3, IL6, and EGFR and immunoexpression of PD-L1 in osteosarcoma patients, while also evaluating their expressions in pediatric and nonpediatric patients." (PMID 38434518, 2024).
osteosarcoma (continued). "A more recent publication indicated that gefitinib, an EGFR inhibitor, reduces osteosarcoma invasion and metastasis in vivo." (PMID 37894336, 2023). "This present study was consistent with reports from earlier studies that treatment with Polygonum cuspidatum, curcumin, and butein inhibited the EGFR-Erk1/2 cascade signaling pathway, resulting in the inhibition of osteosarcoma." (PMID 36765716, 2023). "Given the low-mild expression of EGFR reported in different osteosarcoma cell lines, including Saos-2, the clinical EGFR inhibitor gefitinib has been previously evaluated in vitro and found to have a moderate inhibitory effect on cell proliferation." (PMID 36980255, 2023). "For that, the nanocarriers were labeled with CD133 and EGFR aptamers to selectively target CD133-positive osteosarcoma CSCs and EGFR-overexpressing osteosarcoma cells, respectively." (PMID 38275722, 2023). "Osteosarcoma cells express markedly distinct levels of functional EGFR, which is well-recognized by EGF-mediated downstream cascade activation of Ras, Raf, MEK, and Erk." (PMID 36765716, 2023). "The dose-dependent manners of ononin treatment increased the expression of apoptosis and inhibition of cell proliferation in MG-63 and U2OS osteosarcoma cell lines through the EGFR-Erk1/2 signaling pathways." (PMID 36765716, 2023). "Studies have shown that Wt1 (−KTS) induces programmed cell death through transcriptional repression of the Epidermal Growth Factor Receptor (EGFR) gene in osteosarcoma cells." (PMID 36829196, 2023). "More recent studies indicated CDK6 and EGFR contribute to the development of chemotherapy resistance in osteosarcoma." (PMID 37894336, 2023). "Herein, it is important to highlight the potency of intact ZR2002 in this aggressive osteosarcoma model, with evidence of intratumoral inhibition of EGFR and apparent DNA damage, as detected via H2AX." (PMID 36980255, 2023). "Lastly, the drug sensitivity data from Genomics of Drug Sensitivity in Cancer (GDSC, version 17.3) showed osteosarcoma cell lines with various response to CDK6 or EGFR inhibitors." (PMID 37894336, 2023). "In summary, miR-491-5p inhibited the expression of EGFR, a protein involved in cell survival, and it enhanced the expression of Bak, a pro-apoptotic protein in osteosarcoma cells." (PMID 35337159, 2022). "Circ-ITCH acts in the miR-7/EGFR pathway to promote the migration and invasion of osteosarcoma cells through sponge adsorption." (PMID 36254231, 2022). "Specifically, EGFR expression was significantly upregulated in osteosarcoma lung metastasis compared to the extrapulmonary sites." (PMID 36432687, 2022). "Osteosarcoma-associated antigens are numerous and complicated, mainly represented by activated leukocyte cell adhesion molecules (CD166), B7H3, and epidermal growth factor receptor." (PMID 35720360, 2022). "This anti-EGFR targeted multifunctional I-131 radio-nanotherapeutic signifies a customizable specific targeted treatment for osteosarcoma." (PMID 36234645, 2022). "In this study, the EGFR expression level of osteosarcoma samples was verified by immunohistochemical staining." (PMID 36052285, 2022). "EGFR is expressed in a range of sarcoma subtypes, including soft tissue sarcomas (~78%) and osteosarcomas (57%)." (PMID 34572932, 2021). "EGFR was reported to be abnormally expressed in osteosarcoma, and the expression as well as amplification of EGFR were observed in the osteosarcoma with high grade (PMID:)." (PMID 34335109, 2021). "Mechanistically, mass spectrum analysis showed that MYLK4 interacted with the epidermal growth factor receptor (EGFR) in osteosarcoma cells and promoted growth and metastasis via the EGFR signaling pathway." (PMID 33980265, 2021). "The small molecule VEGFR and EGFR inhibitor ZD6474 was able to reduce tumour growth in an osteosarcoma mouse model and had a synergistic effect with the COX2-inhibitor celecoxib in vitro and in vivo." (PMID 32961800, 2020).
osteosarcoma (continued). "In osteosarcoma (OS), only tumors expressing both epidermal growth factor receptor (EGFR) and c-Fos respond to anti-EGFR therapy." (PMID 33488748, 2020). "EGFR and Her4 have also been detected in osteosarcoma samples, and one study reported EGFR protein overexpression in 50% (6/12) of osteosarcoma cell lines tested." (PMID 32961800, 2020). "There is additional preclinical evidence that active EGFR signalling is important for osteosarcoma progression." (PMID 32961800, 2020). "While results were promising, further investigations are necessary to confirm the efficacy and safety of SC for osteosarcoma treatment, either as monotherapy or in combination with EGFR signaling inhibitors." (PMID 31422383, 2019). "Overactive EGFR signaling is frequently seen in osteosarcoma cells, and represents a potential therapeutic target." (PMID 31422383, 2019). "Cetuximab, a mAb that targets epidermal growth factor receptor (EGFR) on target cells, with an Fc region that binds to CD16 on NK cells, increases NK-dependent lysis of EGFR-expressing osteosarcoma cell lines by enhancing ADCC." (PMID 31156651, 2019). "Previous studies revealed that EGFR gene copy number amplification and EGFR overexpression are common events in osteosarcoma, so targeting EGFR signaling is a promising therapeutic goal." (PMID 31422383, 2019). "Western blotting was carried out to determine the expression of total and phosphorylated STAT3 and EGFR levels in osteosarcoma cells after combined treatment with SC and erlotinib." (PMID 31422383, 2019). "We indeed previously reported that metastatic and recurrent osteosarcoma tumors expressed higher EGFR and PDGFRα levels than localized tumors." (PMID 30642298, 2019). "The effect of STAT3 and EGFR co-inhibition on osteosarcoma cell viability was evaluated by calculating drug combination index (CI) values using the MTT assay." (PMID 31422383, 2019). "Xenografted SPC24 knockdown osteosarcoma cells showed reduced tumor growth in nude mice with decreased EGFR and phospho-ERK levels and increased E-cadherin levels." (PMID 29285250, 2017). "The discovery of targetable oncogenes led to the routine molecular testing for gene mutations, such as those genes encoding epidermal growth factor receptor (EGFR) and BRAF V600E, ALK, the rat osteosarcoma (ROS1), FLT3, and IDH1/2." (PMID 29195503, 2017). "This study examined the effects of the small molecule EGFR inhibitor erlotinib on canine osteosarcoma radiation responses, target and downstream protein expression in vitro." (PMID 27245053, 2016). "Epidermal growth factor receptor (EGFR) expression has been documented in canine osteosarcoma and higher EGFR levels have been correlated to a worse prognosis." (PMID 27245053, 2016). "Through the detection of protein and RNA levels, we found that the EGFR in osteosarcoma tissue was higher than that in adjacent tissues." (PMID 27830833, 2016). "In osteosarcoma, in vitro data from early passage osteosarcoma cells demonstrate constitutive EGFR phosphorylation whose abrogation leads to growth inhibition." (PMID 27830833, 2016). "Aim of this study was to investigate the influence of EGFR inhibition on cell viability and its interaction with chemotherapy response in osteosarcoma cell lines." (PMID 26526352, 2015). "Osteosarcoma cells expressed distinctly differing levels of functional EGFR reaching in some cases high amounts." (PMID 26526352, 2015). "We determined that AREG increases the expression of intercellular adhesion molecule-1 (ICAM-1) through PI3K/Akt signaling pathway via its interaction with the epidermal growth factor receptor, thus resulting in the enhanced cell migration of osteosarcoma." (PMID 26503469, 2015). "In the present study, we investigated the impact of EGFR inhibition on osteosarcoma cell behaviour and its interaction with chemotherapy response." (PMID 26526352, 2015).